TARM1 (T cell-interacting, activating receptor on myeloid cells 1)
Description:
May act as receptor (By similarity). Negatively regulates TCR-mediated CD4(+) T cell proliferation and activation, possibly by binding an unknown ligand on the T cell surface. Enhances Toll-like receptor-mediated production of pro-inflammatory cytokines by macrophages and neutrophils (By similarity).
Synonyms: OLT-2
Tractability: Antibody: UniProt places it where antibodies can reach, with high confidence; its Gene Ontology location is reachable by antibodies, with high confidence; UniProt predicts a signal peptide or a membrane-spanning region.
Gene: Protein-coding gene on chromosome 19 (54,069,895 to 54,081,365, reverse strand). Ensembl gene ENSG00000248385.
Subcellular location: Cell membrane
Pathways (Reactome):
Immune System: Neutrophil degranulation
Gene Ontology:
Molecular function: immunoglobulin receptor binding; transmembrane signaling receptor activity
Biological process: negative regulation of CD4-positive, alpha-beta T cell activation; negative regulation of CD4-positive, alpha-beta T cell proliferation; signal transduction
Cellular component: plasma membrane; specific granule membrane; tertiary granule membrane
Genetic constraint (gnomAD): Loss-of-function variants: 24 observed, 31.5 expected, observed/expected ratio (o/e) 0.76, 90% interval 0.55 to 1.07. The upper end of that interval is the gene's LOEUF score, 1.07, which puts it in group 4 of 6, group 1 being the genes least tolerant of losing a copy. Missense variants: 323 observed, 342.3 expected, observed/expected ratio (o/e) 0.94, 90% interval 0.86 to 1.03. Synonymous variants: 129 observed, 142.1 expected, observed/expected ratio (o/e) 0.91, 90% interval 0.79 to 1.05.
Homologues: Orthologues: chimpanzee TARM1 (95% identical), macaque TARM1 (80% identical), mouse Tarm1 (50% identical), rat Tarm1 (50% identical), tropical clawed frog xilr1 (27% identical). Paralogues in human: GP6 (35% identical), IGSF1 (33% identical), OSCAR (32% identical), LILRB5 (31% identical), LILRA2 (31% identical), LILRB1 (31% identical), LILRB3 (31% identical), LILRA1 (30% identical), LILRA6 (30% identical), LILRB2 (30% identical), LILRA5 (30% identical), A1BG (29% identical), and 13 more.
Diseases named in the same sentence as TARM1 in open-access papers:
TARM1 is named in the same sentence as 10 diseases in open-access papers, as found by Europe PMC text mining. Sharing a sentence is not in itself a finding about the gene and the disease. The quoted sentences say what the papers report.
Arthritis (2 papers, 2019 to 2021). Inflammation of a joint. "The incidence of arthritis in Tarm1–/– mice was significantly reduced and the severity score was also markedly attenuated throughout the disease stages compared with wild-type (WT) mice." (PMID 33397982, 2021). "Here the authors show that TARM1 binds collagens to activate dendritic cells and thereby is an effector of inflammatory arthritis, plus provide a soluble TARM-Fc fusion protein that can limit collagen-induced arthritis in mice." (PMID 33397982, 2021).
autoimmune disease (1 paper, 2021). A disorder resulting from loss of function or tissue destruction of an organ or multiple organs, arising from humoral or cellular immune responses of the individual to their own tissue constituents. "Furthermore, we show that administration of soluble TARM1 attenuates the development of CIA in mice, suggesting that TARM1 is a good target for the treatment of autoimmune diseases." (PMID 33397982, 2021).
rheumatoid arthritis (1 paper, 2021). A chronic, systemic autoimmune disorder characterized by inflammation in the synovial membranes and articular surfaces. "Here, we show that Tarm1 expression is elevated in the joints of rheumatoid arthritis mouse models, and the development of collagen-induced arthritis (CIA) is suppressed in Tarm1–/– mice." (PMID 33397982, 2021).
cancer (2 papers, 2021 to 2026). A tumor composed of atypical neoplastic, often pleomorphic cells that invade other tissues. "These mAbs provide valuable tools for dissecting TARM1-mediated function and represent a potential approach for therapeutic strategies in inflammatory diseases and cancer." (PMID 41957528, 2026). "Seven upregulated genes (≥2.0-fold), Ccl24 (4.8-fold), Ccl17 (3.9-fold), S100a8 (2.9-fold), Tarm1 (2.7-fold), Anxa10 (2.4-fold), Ptgs2 (2.0-fold), and Ccl22 (2.0-fold) were detected as inflammatory and cancer-promoting genes." (PMID 34948416, 2021).
TARM1 also shares sentences with these, for which no sentence is quoted: allergic disease (1 paper); asthma (1); infection (1); Sepsis (1); tumor (1); uveitis (1).